TGM4 (transglutaminase 4)
Description:
Associated with the mammalian reproductive process. Catalyzes the cross-linking of proteins and the conjugation of polyamines to specific proteins in the seminal tract.
Synonyms: TGP; hTGP
Tractability: Antibody: its Gene Ontology location is reachable by antibodies, with high confidence.
Gene: Protein-coding gene on chromosome 3 (44,874,608 to 44,914,990, forward strand). Ensembl gene ENSG00000163810.
Gene Ontology:
Molecular function: protein-glutamine gamma-glutamyltransferase activity
Biological process: peptide cross-linking
Cellular component: cytoplasm; extracellular exosome; extracellular matrix; Golgi apparatus
Genetic constraint (gnomAD): Loss-of-function variants: 64 observed, 81.43 expected, observed/expected ratio (o/e) 0.79, 90% interval 0.64 to 0.97. The upper end of that interval is the gene's LOEUF score, 0.97, which puts it in group 4 of 6, group 1 being the genes least tolerant of losing a copy. Missense variants: 794 observed, 884.99 expected, observed/expected ratio (o/e) 0.9, 90% interval 0.85 to 0.95. Synonymous variants: 337 observed, 347.53 expected, observed/expected ratio (o/e) 0.97, 90% interval 0.89 to 1.06.
Homologues: Orthologues: chimpanzee TGM4 (99% identical), macaque TGM4 (94% identical), guinea pig TGM4 (57% identical), rat Tgm4 (54% identical), mouse Tgm4 (54% identical), tropical clawed frog tgm4 (44% identical), Drosophila melanogaster Tg (32% identical). Paralogues in human: TGM1 (37% identical), TGM7 (35% identical), TGM6 (34% identical), TGM2 (33% identical), TGM5 (33% identical), TGM3 (32% identical), F13A1 (31% identical), EPB42 (27% identical).
Diseases named in the same sentence as TGM4 in open-access papers:
TGM4 is named in the same sentence as 18 diseases in open-access papers, as found by Europe PMC text mining. Sharing a sentence is not in itself a finding about the gene and the disease. The quoted sentences say what the papers report.
prostate carcinoma (14 papers, 2007 to 2025). A carcinoma that arises from epithelial cells of the prostate gland. "EVs associated with prostate cancer have been found to express TGM4." (PMID 40214422, 2025). "Additionally, further investigations have identified a set of androgen-responsive genes such as transglutaminase 4 (TGM4) that could serve as potential tumor-associated antigens (TAAs) for prostate cancer." (PMID 37895076, 2023). "Together, these findings suggest TGM4 as a cell progression factor in prostate cancer via the promotion of adhesion, growth, migration, invasion, and EMT." (PMID 40214422, 2025). "Knockdown of TGM4 by ribozyme transgene reduced adhesion, motility, and invasiveness of CAHPV-10 prostate cancer cells, while forced expression of TGM4 increased adhesion, motility, and invasion of PC-3 prostate cancer cells." (PMID 40214422, 2025). "In contrast, downregulated expressions of TGM4 have also been reported in certain prostate cancer cells." (PMID 40214422, 2025). "Transglutaminase 4 (TGM4) is often highly expressed in prostate cancer and its expression levels in EV isolated from urine were strongly associated with prostate cancer." (PMID 33114768, 2020). "Western blot analysis together with immunohistochemical analysis demonstrated TGM4 downregulation in prostate cancer." (PMID 31360119, 2019). "Other genes identified as highly enriched in prostate cancer were TGM4, KLK2 and KLK4, the latter kalekrein-related proteins belonging to the same family as PSA (KLK3)." (PMID 26237329, 2015). "Five of these top seven genes namely, MYLK, KLK2, KLK3, LTF and TGM4 had already been specifically related to prostate carcinoma." (PMID 19055846, 2008). "Even though no direct androgen regulation has been reported for the TGM2 gene, another transglutaminase enzyme (TGM4) has been found to be androgen regulated in human prostate cancer cell lines." (PMID 17553164, 2007). "Consistent with this, TGM4 expression is upregulated in prostate cancer." (PMID 40214422, 2025). "However, the role of TGM4 in the survival of prostate cancer needs to be investigated, particularly considering its opposing effect on MDA-7/IL-24." (PMID 40214422, 2025). "Moreover, TGM4 overexpression in PC-3 prostate cancer cells reversed the adhesion, growth, and migration inhibitory effect of melanoma differentiation-associated gene-7/interleukin-24 (MDA-7/IL-24)." (PMID 40214422, 2025). "This may suggest a wide range of TGM4 expressions in prostate cancer." (PMID 40214422, 2025). "The MYLK, KLK2, KLK3, HAN11, LTF, CSRP1 and TGM4 genes presented significant changes in their functional connectivity between normal and tumoral conditions and were also classified as the top seven most informative genes for the prostate cancer genesis process by our discriminant analysis." (PMID 19055846, 2008). "Corroborating these findings, TGM4 overexpression increased migration of PC-3, PZ-HPV-7, and DU145 prostate cancer cells, while TGM4 knockdown by ribozyme transgene reduced EMT of CAHPV-10 prostate cancer cells." (PMID 40214422, 2025). "In a mouse prostate cancer model generated by deletion of the prostate epithelium-specific tumor suppressor PTEN, TGM4 was rapidly downregulated and the dedifferentiation of the prostatic epithelium was quicker than in organ-confined human prostate cancers." (PMID 31360119, 2019). "It is important to note that well known prostate cancer biomarkers including PSA, FOLH1/PMSA, TGM4, and TMPRSS were also found to be enriched in urinary exosomes from prostate cancer patients compared to controls." (PMID 26196085, 2015).
prostate tumors (3 papers, 2013 to 2023). "Transglutaminase 4 (TGM4) expression is primarily confined to the luminal epithelia of prostate tumors, and TGM4-pulsed monocyte-derived DCs (moDCs) expanded CD8+ and CD4+ T cells, thus making TGM4 a potential vaccine candidate to treat PCa." (PMID 37738978, 2023). "In this study, we demonstrated that 255 DEGs were up/down-regulated in prostate tumors compared with BPH tissues; qRT-PCR also confirmed that the DEGs such as ITGBL1, KRT15, TGM4, and HOXA7 genes were up/down-regulated in PCa tissue and cell lines." (PMID 29285211, 2017).
prostatitis (2 papers, 2016 to 2020). An infectious or non-infectious inflammatory process affecting the prostate gland. "Accordingly, Aire−/− mice develop TGM4 autoantibodies, have compromised TGM4 secretion, prostatitis, and are subfertile." (PMID 32529252, 2020). "Recently, several novel autoantigens have been identified using proteome arrays, including the prostate-specific enzyme transglutaminase 4 (TGM4) associated with male infertility and prostatitis in Aire-knockout mice." (PMID 27253668, 2016).
autism spectrum disorder (1 paper, 2017). A spectrum of developmental disorders that includes autism, and Asperger syndrome. "A homozygous TGM4 LOF variant was also identified in the Simons Simplex Collection (SSC) dataset, a project aimed to improve the understanding and research of autism spectrum disorders." (PMID 28248968, 2017).
Azoospermia (1 paper, 2021). Absence of any measurable level of sperm,whereby spermatozoa cannot be observed even after centrifugation of the semen pellet. "Additionally, germ cell-specific (DEAD-box helicase 4), seminal vesicle-specific (Semenogelin 1), and prostate-specific (Transglutaminase 4) mRNAs in seminal plasma could be markers for identifying the presence of germ cells or the rough localization of complete obstructive azoospermia." (PMID 35211476, 2021).
gastric cancer (1 paper, 2020). A primary or metastatic malignant neoplasm involving the stomach. "In contrast, other transglutaminases including TGM1, TGM4, TGM5, TGM6, and TGM7 exhibited a significant decrease in gene expression in the gastric cancer tissue samples." (PMID 32467608, 2020).
pancreatic carcinoma (1 paper, 2021). "This work highlights the importance of lipid signaling in cancer and the use of synthetic lipid structures, as TGM4, as a novel approach to treat pancreatic cancer and other neoplasias." (PMID 35126175, 2021). "In this work, we studied the activity of a synthetic triacylglycerol, TGM4, on cellular and in vivo models of pancreatic cancer." (PMID 35126175, 2021). "Our in vitro studies clearly showed that TGM4 decreases the number of viable pancreatic tumor cells (Mia-PaCa-2 and PANC-1) in a time- and concentration-dependent manner." (PMID 35126175, 2021). "We demonstrated that TGM4 inhibited proliferation of Mia-PaCa-2 (human pancreatic carcinoma) and PANC-1 (human pancreatic carcinoma of ductal cells) in in vitro models and in an in vivo xenograft model of Mia-PaCa-2 cells." (PMID 35126175, 2021).
parasite infection (1 paper, 2025). "In future studies, it would be interesting to target TGM4 by active or passive immunisation and monitor the effects on myeloid cell subsets during parasite infection." (PMID 39609640, 2025).
varicocele (1 paper, 2015). A condition characterized by the dilated tortuous veins of the spermatic cord with a marked left-sided predominance. "Our data shows that TGM4 was overexpressed with high abundance in the unilateral varicocele group." (PMID 25890347, 2015). "However, in Del Guidice’s study, TGM4 was found only to be expressed in samples after varicocelectomy, but not prior to varicocele removal." (PMID 25890347, 2015).
tumor (9 papers, 2008 to 2023). "We demonstrated that TGM4 induces pancreatic cell death by the activation of autophagy and related signal transduction events in cell cultures and reduces tumor growth in an in vivo xenograft model." (PMID 35126175, 2021). "Identification of seven genes (MYLK, KLK2, KLK3, HAN11, LTF, CSRP1, TGM4) which have their connectivity altered between normal/tumoral conditions may provide novel insights into specific targets against tumor progression." (PMID 19055846, 2008). "In addition, TGM4, TGM6, and TGM7 genes were the lowest expressed and did not exhibit statistically significant differences in the level of expression between tumor and healthy tissues." (PMID 35725560, 2022).
cancer (4 papers, 2011 to 2022). A tumor composed of atypical neoplastic, often pleomorphic cells that invade other tissues. "Putative exons 7, 10 and 11 were down-regulated, while seven other putative exons were up-regulated, which suggests there could be multiple splice variants; this is the case for human transglutaminase 4 in cancer tissues." (PMID 23497009, 2013). "TGM4 and SCGB1A1 have been among down-regulated mRNAs in this type of cancer." (PMID 36497036, 2022).
infection (3 papers, 2015 to 2025). The state of being infected such as from the introduction of a foreign agent such as serum, vaccine, antigenic substance or organism. "Thus, by targeting CD49d, TGM4 can encompass multiple immune cell subsets that are instrumental to protective immunity against infection." (PMID 39609640, 2025). "The last group of genes included IL-1β, CXCLi2 (IL-8), AVD, IRG1, iNOS, ExFABP, TGM4 and SAA whose expression in HD11 cells increased after the infection with S. Enteritidis." (PMID 26380970, 2015).
TGM4 also shares sentences with these, for which no sentence is quoted: thyroid cancer (2 papers); autoimmune polyendocrine syndrome type 1 (1); lung adenoma (1); male infertility (1); melanoma (1); neurodegenerative disease (1).